EGFR (epidermal growth factor receptor)
Diseases named in the same sentence as EGFR in open-access papers (continued):
Sharing a sentence is not in itself a finding about the gene and the disease.
breast carcinoma (continued). "In order to find another specific inhibitor of ErbB2 that might have few effects on EGFR, we also tested trastuzumab, a specific antibody against ErbB2 routinely used in the treatment of advanced breast cancers." (PMID 29662626, 2018). "In addition, hDiSNet provides the insights of the FGFR (EGFR)-MAPK pathway for interpreting the mechanisms of breast cancer and ErbB signaling pathway in brain cancer." (PMID 29560828, 2018). "One of the current treatment options for breast cancer is EGFR-TKI as well as anti-hormone agents." (PMID 30497501, 2018). "Together with our findings using the EGFR-AA construct, these data suggest a mechanism in which more migratory and metastatic breast cancer cells undergo an increased rate of nuclear rupture and repair and thus sample more activated EGFR molecules from endosomes." (PMID 30250119, 2018). "To investigate whether a functional linkage exists between TGF‐β and EGFR signaling pathways, we treated two breast cancer cells with TGF‐β for 48 h and examined the mRNA and protein expression levels of EGFR." (PMID 29215776, 2018). "The stringent up-regulation of SGK1 in response to progesterone led to an activation of a tumor metastasis suppressor gene, NDRG1, via a set of AP-1 network genes to inactivate AKT1, ERK1/2, and EGFR kinases, impeding the invasion and migration of breast cancer cells." (PMID 30337371, 2018). "Therefore, EGFR holds the potential to be an attractive drug target in breast cancer, and the EGFR inhibitors, including small molecule inhibitors and monoclonal antibodies (mAbs), have been developed and some are currently used in clinics." (PMID 29455658, 2018). "Using optical imaging, pre-clinical data in breast cancer cell lines showed that gefitinib, an EGFR tyrosine kinase inhibitor, significantly reduced the uptake of choline metabolites in the sensitive cell line BT-474 but not in the resistant cell line MDA-MB-231." (PMID 29983881, 2018). "In addition, own studies showed the relevance of the PTPIP51/c-Src interaction in correlation with the sensitivity of Her2 positive breast cancer cells to EGFR/Her2 targeted TKIs." (PMID 30360441, 2018). "In addition, a specific mutant EGFR, EGFRvIII, overexpressed on breast carcinomas, lung carcinomas, and other tumors, can be recognized by scFv mutant receptor 1 (MR1)." (PMID 30799657, 2018). "EGFR is also essential for TGF‐β‐induced enhancement of these abilities of breast cancer cells." (PMID 29215776, 2018). "In addition, ectopic over-expression of EGFR partially reversed the miR-539-inhibited proliferation and migration of breast cancer cells." (PMID 29391441, 2018). "Expression of the proto-oncogene and receptor tyrosine kinase EGFR was correlated with cell proliferation, survival, migration, and differentiation, and its over-expression can lead to the development and recurrence of breast cancer." (PMID 30140169, 2018). "Researchers have shown efficient cellular and nuclear uptake of 111In-labeled anti-EGFR immunoconjugates with and without NLS-conjugation, which resulted in effective cell kill and localization at the tumor site as visualized by SPECT in EGFR-overexpressing breast cancer MDA-MB-468 xenografts." (PMID 30233374, 2018). "Overexpression of EGFR is observed in 20–30% of breast carcinoma." (PMID 30241301, 2018). "Interestingly, the human tumor EC-like population had high plasma membrane EGFR and IGFR concentrations (~21,000/cell and ~20,000/cell, respectively), consistent with qualitative findings of higher EGFR on breast carcinoma-derived ECs compared to normal ECs." (PMID 30050899, 2018). "MYOF may act as a key regulator in epidermal growth factor receptor (EGFR) degradation after its activation and internalization in breast cancer cells." (PMID 30213946, 2018).
breast carcinoma (continued). "Follow-up studies demonstrated that ST8SIA1 maintains stem cell phenotype in breast CSCs, and that GD3 synthases may be involved in gefitinib-resistance of epidermal growth factor receptor (EGFR)-positive breast cancer cells." (PMID 29773994, 2018). "Inhibition of Akt1 using MK2206 could induce an increase in the expression of EGFR and β-catenin in breast cancer cells." (PMID 30445978, 2018). "The interplay between TGF‐β signaling and EGFR is also confirmed in breast cancer cell lines." (PMID 29215776, 2018). "To verify whether Sp1 is essential for the transcriptional activation of EGFR, we treated breast cancer cells with a Sp1 inhibitor MTM." (PMID 29215776, 2018). "The crosstalk of ER α with HER2 and the other members of the epithelial growth factor receptor (EGFR) family are well known, widely reported, and are commonly considered among the reasons responsible for breast cancer progression following the development of endocrine resistance." (PMID 29099748, 2017). "In addition, OSU03013 has been used in breast cancer treatment, and it has been found to have a higher cytotoxicity especially in breast cancer cells with epidermal growth factor receptor (HER)-2 overexpression." (PMID 29130448, 2017). "Anti-EGFR autoantibody levels were also determined in the sera of breast cancer patients as well and showed that they were negatively correlated with the disease-free survival only in the group of breast cancer patients, with relapse or death." (PMID 29354119, 2017). "Similarly, the combination of an EGFR-CAR-modified NK92 cell line therapy with the oncolytic herpes simplex virus 1 (oHSV-1) is a promising strategy for the treatment of EGFR-positive breast cancer that has metastasized to the brain." (PMID 28488245, 2017). "Similarly, EVs can be modified to display an epidermal growth factor receptor (EGFR)-binding peptide GE11 on their surface for targeted delivery of a therapeutic miRNA to xenograft breast cancer tissues that express EGFR." (PMID 28326166, 2017). "Moreover, we introduce an additional level of crosstalk between hypoxia/PHD2-mediated signaling and EGFR-induced tumorigenesis in breast cancer, which is important for the development of novel breast cancer treatment options." (PMID 28038470, 2017). "EGFR is often present in excessive amounts in human breast cancers." (PMID 28079144, 2017). "In addition, FFA1 has been shown to induce ERK1/2 activation through a mechanism involving Src kinase and EGFR transactivation by oleic acid in the breast cancer cell lines MCF-7 and MDA-MB-231." (PMID 28747926, 2017). "However, recent findings suggest that there are fundamental changes in EGFR signaling that take place during primary tumor invasion, dissemination and ultimate metastasis of breast cancer cells." (PMID 28435746, 2017). "Nuclear EGFR has been observed in various cancers, including breast cancer, NSCLC, and SCCHN." (PMID 29140271, 2017). "We therefore next examined whether WT161 could downregulate EGFR and/or other receptor expression in breast cancer cells." (PMID 29113288, 2017). "The T-P network of these herbs constructed presently demonstrates that the herbal medicines may simultaneously target several pathways like EGFR, Estrogen and Wnt signaling pathways, thereby exhibiting synergistic benefits in breast cancer treatment." (PMID 28068355, 2017). "Claudin-low tumors represent ~5-10% of all breast cancers, are often triple-negative and poorly differentiated, and have elevated activities of EGFR, proto-oncogene tyrosine kinase Src, transforming growth factor β (TGFβ), and signal transducer and activator of transcription 3 (STAT3) pathways." (PMID 28148288, 2017). "BPA is reported to activate GPR30/EGFR/ERK transduction pathway in SKBR3 breast cancer cells and cancer-associated fibroblasts (CAFs) lacking the classical estrogen receptor (ER)." (PMID 29383186, 2017).
breast carcinoma (continued). "Additionally, recent studies have shown that CD73 also affects tumor cells via the EGFR signaling pathway in breast cancer and colorectal cancer." (PMID 28158983, 2017). "This study suggests that breast cancer tumors expressing EGFR and IKKε may be potential targets for drugs aiming at inhibiting IKKε activity or expression." (PMID 28532474, 2017). "Likewise, Vandetanib (B) has been found to be a selective inhibitor that targets the vascular endothelial growth factor receptor (VEGFR) and the EGFR signal transduction pathways for the treatment of breast cancer." (PMID 29156606, 2017). "A specific region of EGFR has an enhancer activity in breast cancer cell lines overproducing EGFR." (PMID 28574446, 2017). "Furthermore, we confirmed the EGFR-signaling-dependent expression of GBP1 in breast cancer cell lines via qPCR." (PMID 29115931, 2017). "Two of these patients, one with HER-2 positive breast cancer and other with EGFR wild-type lung adenocarcinoma, experienced neurological worsening and needed salvage therapy using repeat BV, resulting in immediate and durable symptomatic relief and radiological stabilisation for more than 20 months." (PMID 29110648, 2017). "Whether ADAM12 activates EGFR in breast cancer cells and, in particular, whether ADAM12-mediated EGFR activation promotes the acquisition of the breast CSC phenotype, has not been sufficiently explored." (PMID 28148288, 2017). "In this report authors show that EGFR may induce PD-L1 surface stabilization by inhibiting GSK3β in basal-like breast cancer cells." (PMID 28611673, 2017). "In a murine model of basal-like breast cancer, we demonstrated a significant degree of intratumoral heterogeneity in EGFR activity, as well as the pharmacodynamic effect of a radionuclide-labeled EGFR inhibitor in situ." (PMID 28166195, 2017). "Therefore, we demonstrated that heterodimerization of EGFR and HER2 contributes more to the aggressiveness of breast cancer than EGFR homodimerization." (PMID 28881584, 2017). "EGFR is an important marker in breast carcinoma pathology, a potential target of new therapies." (PMID 28465354, 2017). "In addition, we demonstrated that GBP1 expression is controlled by EGFR signaling in breast cancer cells." (PMID 29115931, 2017). "Several previous reports found KIAA1199 was involved in EGFR and Wnt signaling pathways in breast cancer, cervical cancer and colon cancer, nevertheless, the mechanism of KIAA1199 in GC still remains unknown." (PMID 28422983, 2017). "In this work, we investigated the ability for EGFR-NS to bind breast cancer cell lines expressing different levels of EGFR and provide enhanced colorimetric signal relative to freely delivered EGFR antibodies, thus improving upon ELISA-based detection technology." (PMID 28494030, 2017). "Combination therapy with MEK inhibitor trametinib and EGFR/HER2 dual inhibitor lapatinib has shown a synergistic effect and circumvented the resistance of MEK1‐mutated gastric cancer cells and HER2‐positive breast cancer cells to MEK inhibitors." (PMID 28632938, 2017). "To gain further support of the role of the ZNF516–CtBP/LSD1/CoREST–EGFR axis in the development and progression of breast cancer and to extend our observations to a clinicopathologically relevant context, we first profiled the expression pattern of ZNF516 and EGFR in breast cancer cell lines." (PMID 28947780, 2017). "Interestingly, Ship2 modulates EGFR (Epidermal Growth Factor Receptor) signaling: down-regulation of Ship2 in breast cancer cell lines improves EGFR internalization and degradation and arrests cell proliferation." (PMID 29234063, 2017). "Moreover, nuclear EGFR (nEGFR) can enhance resistance to anti-EGFR therapies and correlates with poor overall survival in breast cancer." (PMID 29115931, 2017).
breast carcinoma (continued). "Cheang MC put forward that the special type (ER−/PR−/HER2−/cytokeratin 5+ and/or EGFR+) of basal-like breast cancers might have cancer stem-like properties and the strong tendency to metastasize early." (PMID 29088770, 2017). "For instance, in a study on breast cancer, activated miR-146a may attenuate epidermal growth factor receptor expression, thus influencing the disease progression, and clinical prognosis." (PMID 27901485, 2017). "We recently described a class of agents termed Disulfide bond Disrupting Agents (DDAs) that are capable of breaking disulfide bonds in solution, and when applied to breast cancer cells downregulate HER family members EGFR, HER2, and HER3 in parallel, and inactivate Akt." (PMID 28423644, 2017). "Conversely, treatment with Lapatinib, a small molecule EGFR/Erbb2 inhibitor used to treat breast cancer, has not been linked to cardiotoxicity." (PMID 28924210, 2017). "Importantly, miR-338-3p inhibition or EYA2 knockdown greatly attenuated the ability of EGFR to regulate breast cancer cell proliferation." (PMID 28703807, 2017). "An integrative microarray data analysis using the Kaplan Meier Plotter shows that low EcSOD expression is associated with significantly reduced relapse free survival in all breast cancer subtypes, including the basal-like (ER−, PR−, Her2−, CK 5/6+, and/or EGFR+) breast cancers." (PMID 29296173, 2017). "Similar effects were seen upon local application of NK-92 cells equipped with CARs that recognize EGFR, mutant EGFRvIII, or both antigens against orthotopic EGFR- and/or EGFRvIII-positive glioblastoma xenografts or breast cancer brain metastases growing in NSG mice." (PMID 28572802, 2017). "Based on this evidence, we propose that GD3S contributes to gefitinib-resistance in EGFR-positive breast cancer cells and may be an effective therapeutic target in drug-resistant breast cancers." (PMID 28537895, 2017). "The results showed that ZNF516 overexpression had a significant inhibitory effect on breast cancer cell proliferation, a phenotype that could be rescued by simultaneous overexpression of EGFR." (PMID 28947780, 2017). "In addition, expression of constitutively active truncated EGFR vII protein that lacks extracellular domain in breast cancer (20–78%) contributes to the aggressiveness of tumor." (PMID 29119846, 2017). "Moreover, we showed that GBP1 expression was controlled by epidermal growth factor receptor (EGFR) in breast cancer cell lines." (PMID 29115931, 2017). "Consistently, depletion of ZNF516 promoted breast cancer cell proliferation, an effect that could be abrogated, at least partially, by co-knockdown of EGFR." (PMID 28947780, 2017). "In addition, a PHS treatment reduces the interaction of EGFR with the downstream JAK1/STAT3 signaling network in breast cancer cells." (PMID 29100426, 2017). "In breast cancer, activated EGFR has been shown to transactivate Axl." (PMID 27611946, 2017). "In this study, we analyzed CNR2, IGF-IR and EGFR expression in ERα- and ERα+ breast cancer cells." (PMID 27213582, 2017). "EGFR is also a famous oncogene in ovarian cancer, breast cancer, and gastric cancer." (PMID 28694563, 2017). "In breast cancer cells, inhibition of EGFR signaling reduces breast cancer cell invasion." (PMID 29212252, 2017). "In order to determine real-time kinetics and affinity of 99mTc-DTPA-can225IgG towards native canine EGFR, a competition binding assay using Ligand Tracer® Yellow was performed and the uptake of the radioactive compound in Sh1b canine mammary carcinoma cells was measured." (PMID 29137329, 2017). "ERβ1 represses EMT by destabilizing EGFR in basal-like breast cancer." (PMID 28583190, 2017). "Next, we determined whether EGFR promotes breast cancer cell migration, invasion and EMT via the miR-338-3p/EYA2 axis." (PMID 28703807, 2017).
breast carcinoma (continued). "We conclude that EGFR controls GBP1 expression in breast cancer cells." (PMID 29115931, 2017). "It is currently unknown if similar genetic or/and epigenetic abnormalities of ZNF516 also occur in breast cancer, and it is unclear the sequence of the events associated with the aberrant expression of ZNF516 and EGFR." (PMID 28947780, 2017). "Our finding that the PAD inhibitor, BB-Cl-Amidine, suppresses EGF-induced tumor cell migration, raises the possibility that PAD inhibitors could function in therapeutic formulations for treating EGFR-overexpressing breast cancers." (PMID 28549415, 2017). "In this study, dual-color fluorescence observations for two kinds of membrane proteins, EGFR and EpCAM, were detected with a plasmonic chip by using surface plasmon-enhanced fluorescence microscopy in two kinds of breast cancer cell lines, MDA-MB-231 and MCF-7." (PMID 29257118, 2017). "Lapatinib is a dual HER2/EGFR kinase inhibitor used in patients with HER2-positive breast cancers." (PMID 28369073, 2017). "In breast cancer patients, miR-338-3p expression negatively correlates with the expression of EGFR and EYA2, EGFR status positively associates with EYA2 expression, and miR-338-3p and EYA2 predict breast cancer lung metastasis when expressed in primary breast cancers." (PMID 28703807, 2017). "EGFR was associated with an EMT phenotype of non-metastatic breast cancer patients' CTCs, which co-expressed markers of mesenchymal cells such as vimentin and slug." (PMID 27683128, 2017). "As expected, EGFR enhanced breast cancer cell migration and invasion." (PMID 28703807, 2017). "The present study investigated whether the combination of 25 μg/ml EGCG and 15 or 30 μM IIF could be effective in down-regulating EGFR and markers of migration and invasion in three breast carcinoma cell lines differing in biomolecular characteristics." (PMID 28465354, 2017). "Similarly, the Notch signaling pathway (in KEGG, Reactome, and WikiPathway) cross-talks with EGFR signaling in breast cancer, thus maintaining the cancer cell growth signal through MAPK and PI3K-Akt signaling." (PMID 28288164, 2017). "Activation of ABL1 kinase in NSCLC and breast cancer malignancies has been shown to occur downstream of the EGFR, human epidermal growth factor receptor 2 (HER2), and IGFR, as a late occurring event that contributes to the aggressive growth and metastasis of these solid tumors." (PMID 27086914, 2016). "In contrast to lung adenocarcinomas, which often have EGFR kinase domain mutations that confer resistance to EGFR-TKI treatment, EGFR mutations are lacking or diverse in different clinical breast cancer datasets." (PMID 27590506, 2016). "EGFR amplification, increase in copy number of gene occurs in 15–30% of breast cancer cases." (PMID 26973813, 2016). "Previous findings indicated that EGFR mutations were rare if not absent in breast cancer and thus not a suitable predictor for anti-EGFR targeted therapy." (PMID 27602761, 2016). "In addition to being present on some breast cancer stem cells (CSCs), EGFR plays an important role in cell proliferation, motility, and survival in various tumors including breast cancer." (PMID 27050072, 2016). "Triple-negative breast cancers have been sub-classified into specific molecular subtypes that include basal-like breast cancers (CK5/6-positive and/or EGFR-positive) and claudin-low breast cancers exhibiting low expression of the CDH1 and claudin 3, 4 and 7 genes." (PMID 26988558, 2016). "To further explore whether AXL was involved in E1A-mediated EGFR-TKI sensitization of breast cancer cells, we examined the phosphorylation and expression of AXL in E1A-transfected breast cancer cells." (PMID 27590506, 2016).